DDX17 (DEAD-box helicase 17)
Diseases named in the same sentence as DDX17 in open-access papers (continued):
Sharing a sentence is not in itself a finding about the gene and the disease.
infection (65 papers, 2009 to 2026). The state of being infected such as from the introduction of a foreign agent such as serum, vaccine, antigenic substance or organism. "In anti-COVID-19 research, DDX17 has been identified as a potential host gene affected by infection." (PMID 41367298, 2026). "On the other hand, DDX17 can also function as an antiviral factor in the infection of certain viruses (e.g. HBV and EBV) by inhibiting viral replication." (PMID 41367298, 2026). "Concurrently, these knockdowns significantly diminished DTMUV mRNA and C protein expression post-infection, demonstrating that DDX17 suppression inhibits viral replication." (PMID 41402857, 2025). "Results demonstrated significant increases in both DDX17 mRNA expression and protein abundance proportional to infection duration." (PMID 41402857, 2025). "Based on real-time PCR and Western blot analyses, both the mRNA and protein levels of DDX17 were upregulated in HBV-infected HepG2-NTCP cells on the indicated day after infection." (PMID 35784274, 2022). "DEAD box helicases can also control infection independently of interferon signaling; DDX17 binds an essential stem-loop structure on Rift Valley fever virus RNA to control infection." (PMID 33109765, 2020). "Developing specific inhibitors or small molecules targeting DDX17’s regulatory mechanisms could effectively disrupt the viral replication cycle, thereby limiting viral spread and infection." (PMID 41367298, 2026). "In summary, this study reveals the distinct proviral role of DDX17 in DTMUV infection." (PMID 41402857, 2025). "DDX5 and DDX17 also modulate infection of RNA viruses owing to their RNA-binding properties." (PMID 40257982, 2025). "Confocal microscopy confirmed cytoplasmic co-localization of DDX17 and C protein during infection." (PMID 41402857, 2025). "However, the mechanism of DDX17 in avian viruses remains uninvestigated, and its role in infections by members of the Flavivirus genus represents uncharted territory." (PMID 41402857, 2025). "We also find that DDX5 and DDX17 are important for primary infection of KSHV in endothelial cells." (PMID 40257982, 2025). "Since viral gene transcription was lower upon DDX5/17 knockdown, we hypothesized that DDX5 and DDX17 are important for primary infection." (PMID 40257982, 2025). "Hence, DDX5 and DDX17 aid in primary infection of KSHV in endothelial cells." (PMID 40257982, 2025). "DDX17 and DDX5 relocalize from the nucleus to the cytoplasm upon infection and interact with the viral capsid protein, enhancing RNA replication, protein synthesis, and virion formation." (PMID 41367298, 2026). "Here, we found two host proteins, DDX5 and DDX17, that are required by KSHV and EBV for lytic reactivation, a phase of infection that is important for virus production." (PMID 40257982, 2025). "To determine how DDX5 and DDX17 modulate KSHV lytic reactivation and infection, we wanted to assess the localization of DDX5 and DDX17 and determine if their localization is altered during lytic reactivation." (PMID 40257982, 2025). "It is thus conceivable that the cofactor DDX17 operates with DDX5 within the same complex, carrying out a synergistic or additive function during infection." (PMID 38553727, 2024). "The regulatory mechanisms behind this dual functionality suggest that DDX17 does not simply act as a pro- or anti-viral factor; rather, its role depends on the specific viral type, infection stage, and host cellular environment." (PMID 41367298, 2026). "Our study revealed that DDX17 undergoes no significant nucleocytoplasmic translocation during DTMUV infection despite marked upregulation proportional to infection duration and viral load." (PMID 41402857, 2025). "Utilizing an in vitro infection model combined with CRISPR/Cas9 gene knockout, siRNA interference, and overexpression techniques, we found that DTMUV infection significantly upregulated both mRNA and protein expression levels of DDX17 in host cells." (PMID 41402857, 2025).
infection (continued). "For instance, depletion of DDX17 but not of DDX5 increases infection of Rift Valley Fever virus (RVFV), a segmented, negative-sense RNA virus." (PMID 38553727, 2024). "Similarly, three helicase members, DDX6, DDX17, and DDX23 were shown to restrict the replication of RVFV in Drosophila, in which DDX17 binds the essential stem loop in bunya viral RNA to combat infection." (PMID 31620127, 2019). "Binding of Matrin 3 to DDX17, EXOSC3, and ZAP in uninfected cells may reflect a role for Matrin 3 in alternate host RNA processes, but during infection Matrin 3 may impede ZAP from interacting with these proteins which are needed for optimal RNA degradation activity." (PMID 26129669, 2015). "HIV-luc infection did not increase protein levels of DDX17, EXOSC3, or myc-ZAP2." (PMID 26129669, 2015).
cancer (43 papers, 2014 to 2026). A tumor composed of atypical neoplastic, often pleomorphic cells that invade other tissues. "DDX17, an ATP-dependent RNA/DNA helicase, is implicated in the regulation of RNA metabolism and has been linked to tumorigenesis and metastasis in various cancers." (PMID 40526173, 2025). "In our study, we discovered a positive association between DDX17 expression and regulatory genes involved in RNA methylation for various cancers." (PMID 40526173, 2025). "Further exploration into the underlying mechanisms of DDX17 is likely to enhance our comprehension of its role in tumor biology and offer innovative therapeutic options for individuals with cancer." (PMID 40526173, 2025). "Our analysis revealed a positive association between DDX17 expression and both stromal and immune scores in three distinct types of cancer." (PMID 40526173, 2025). "DEAD box RNA helicase 17 (DDX17) has been shown to be an RNA binding protein involved in RNA metabolism and associated with cancer progression." (PMID 36273228, 2022). "Meanwhile, the heterogeneities characteristic to this type of cancer implying the complexity and originality of its underlying mechanisms require the investigation of the exact role of DDX17." (PMID 36273228, 2022). "When DDX5 and DDX17 expression is abnormal in the physical examination, it indicates that the patient’s health status is poor, with increased the risk of DDX5-/DDX17-associated cancer." (PMID 35992805, 2022). "The multitasking transcriptional regulators DDX5 and DDX17 included in our dataset contain an helicase domain in their structure reported to be associated with cancer development and cell proliferation." (PMID 30971948, 2019). "Additionally, we observed positive correlations between DDX17 and key regulatory genes associated with m6A, m5C, and m1A modifications in multiple cancer types." (PMID 40526173, 2025). "To elucidate the potential role of DDX17 in cancer development via genetic alterations, we analyzed the specific sites and types of mutations within the DDX17, along with RNA modifications and genomic heterogeneity across various cancer types." (PMID 40526173, 2025). "DEAD-box helicase DDX17 is implicated in cancer, viral pathogenesis, and ontogenesis." (PMID 41402857, 2025). "Additionally, Our study did not delve into the molecular mechanisms underlying the role of DDX17 in cancers, leaving this area ripe for future investigation." (PMID 40526173, 2025). "When DDX5/DDX17 expression is disrupted, the body is at great risk of developing cancer." (PMID 35992805, 2022). "Moreover, DDX17 was reported to augment cancer-associated features by inhibiting miRNAs." (PMID 38689093, 2024). "Our aim is to reveal the broad prospects of DDX17 as a prognostic biomarker and therapeutic intervention target through systematic analysis across different cancer types." (PMID 40526173, 2025). "In this study, we discovered the significant overexpression of DDX17 in 27 cancers from TCGA and GTEx databases." (PMID 40526173, 2025). "We found that elevated DDX17 expression was negatively correlated with IC50 values for 30 distinct types of anti-cancer drugs, as per data from the GDSC database." (PMID 40526173, 2025). "While studies have explored the role of DDX17 in specific cancers, further research is needed to understand its mechanisms across different cancer types." (PMID 40526173, 2025). "Expression of DDX17 was associated with patient prognosis, TMB, MSI, and drug sensitivity in certain cancers." (PMID 40526173, 2025). "To address the limitation of normal samples in TCGA, we integrated data from the GTEx database with TCGA to assess DDX17 expression across 29 different cancer types." (PMID 40526173, 2025). "ALDOA lactylation at the K230 and K322 sites causes DDX17 release from ALDOA, allowing DDX17 entry into the nucleus and binding to SRY-box transcription factor 2 (SOX2) to activate their target genes to maintain cancer cell stemness." (PMID 40333742, 2025).
cancer (continued). "We also investigated DDX17 expression across different pathological stages of cancer using the GEPIA2 database." (PMID 40526173, 2025). "We conducted an analysis of DDX17 mRNA expression levels in the TCGA database, and observed elevated expression in six cancer types: CHOL, HNSC, KIRC, LIHC, PRAD, and STAD." (PMID 40526173, 2025). "Conversely, reduced expression of DDX17 was noted in four other cancer types: BLCA, KICH, BRCA, THCA, and UCEC." (PMID 40526173, 2025). "The DDX17 was substantially expressed in the majority of malignancies and was related to pathological staging in cancers such as KIRP, LUAD, THCA, TGCT, and OV." (PMID 40526173, 2025). "Overall, this extensive examination of cancer highlights the importance of DDX17 in prognostic assessment and cancer classification, particularly in relation to immunotherapy." (PMID 40526173, 2025). "We leveraged several public databases, including TIMER, The Cancer Genome Atlas (TCGA), and the Genotype-Tissue Expression (GTEx), to investigate DDX17 mRNA expression across 33 types of tumors." (PMID 40526173, 2025). "This comprehensive analysis enhances our understanding of the potential involvement of DDX17 in pan-cancer." (PMID 40526173, 2025). "At present, research on DDX17 has focused on cancer, and there have been relatively few studies of on-tumor diseases, especially chronic obstructive pulmonary disease." (PMID 38802460, 2024). "For instance, increased production of DDX5 and DDX17 has been linked to tumorigenesis in certain types of cancer, while MBNL1 isoforms have been found to differently affect cancer cell viability and migration." (PMID 37882878, 2023). "In particular, DDX17 affects the pathological progress of cancer through a variety of mechanisms, such as formation of the microprocessor complex, transcriptional regulation, and RNA binding." (PMID 37239217, 2023). "Comparative transcriptome analysis revealed that knockdown of DDX17 led to extensive changes in gene expression profiles and ASEs in A549 cells that were confirmed in The Cancer Genome Atlas (TCGA)-LUAD dataset." (PMID 36164607, 2022). "Second, DDX5 and DDX17 can be used as clinical predictive molecules for predicting cancer recurrence and prognosis." (PMID 35992805, 2022). "The DEAD-box RNA-binding protein (RBP) DDX17 has been found to be involved in the tumorigenesis of many types of cancers." (PMID 36164607, 2022). "HBV is strongly associated with HCC development and DEAD-box RNA helicase 17 (DDX17) is a very important member of the DEAD box family that plays key roles in HCC development by promoting cancer metastasis." (PMID 35784274, 2022). "Third, regulating the posttranslational modification of DDX5/DDX17 can change their functions and targets, improving the tumor response to anticancer drugs and reducing the drug resistance of malignant tumors." (PMID 35992805, 2022). "In most cancers, when DDX5/DDX17 expression levels are elevated, the risk of malignancy is higher, and clinical survival time is shorter." (PMID 35992805, 2022). "This oncogenic effect of DDX17 in LUAD is consistent with the results of studies on other cancer types." (PMID 36164607, 2022). "While controversies regarding the exact role played by DDX17 in diverse cancers have been reported or suggested, the biological function of DDX17 in LUAD has not yet been investigated by systematic approaches." (PMID 36273228, 2022). "In particular, DEAD-box RNA helicase 17 (DDX17) has attracted substantial attention in cancer research because of its vital biological functions in tumorigenesis, proliferation, and especially, metastasis." (PMID 35784274, 2022). "It is necessary to explore the mechanism of action of DDX5/DDX17 in cancer to provide a solid theoretical basis for the application of DDX5/DDX17 in cancer diagnosis and treatment." (PMID 35992805, 2022).
cancer (continued). "The coordinated regulation of miRNA biogenesis and histone modification by DDX17 ubiquitination is the basis of many cancer stem cell-like characteristics." (PMID 35992805, 2022). "The correlation between DDX17 expression and cancer patient was analyzed using RNA-seq data from TCGA project." (PMID 36273228, 2022). "We selected 20 samples with the highest DDX17 expression (all of which are cancer tissues) and 20 samples with the lowest DDX17 expression (including 19 cancer tissues and 1 normal lung tissue) to assess the transcriptional regulation of DDX17." (PMID 36164607, 2022). "DDX17 was significantly overexpressed in a wide variety of cancers (CHOL, LIHC, PRAD, STAD and KIRC) as compared to the corresponding healthy tissues at mRNA level." (PMID 36273228, 2022). "Previous studies have reported that the Hippo pathway regulates miRNA biogenesis through nuclear binding of YAP and sequestration of p72 (DDX17) in cancer." (PMID 33393124, 2021). "However, it is crucial to acknowledge certain limitations despite describing the impact of DDX17 across various types of cancer." (PMID 40526173, 2025). "DDX17 influences cancer initiation and progression through a variety of mechanisms, such as transcriptional regulation, RNA binding, and formation of the microprocessor complex as a member of the Kinesin family, is a crucial regulating factor of chromosome arrangement during mitosis." (PMID 40526173, 2025). "DDX17 expression level varies abnormally in a variety of cancers." (PMID 41322492, 2025). "The expression level of DDX17 is significantly higher in cancers than that in normal tissues, suggesting that DDX17 may play a promotional or predictive role in tumorigenesis and development." (PMID 41322492, 2025). "This analysis revealed significant differential expression of DDX17 among all 29 cancer types." (PMID 40526173, 2025). "Additionally, DDX17 participates in the YAP signaling pathway to increase the stemness of cancer stem-like cells and to promote tumorigenesis and tumor progression." (PMID 40526173, 2025). "DDX17 showed significant differences in expression between cancer and normal tissues." (PMID 40526173, 2025). "The positive correlation between DDX17 and immune infiltration in COAD and READ suggests that DDX17 may enhance anti-tumor immunity in these cancers, making it a potential target for immunotherapy." (PMID 40526173, 2025). "Our study systematically investigated the significant correlation between DDX17 expression and clinical characteristics, prognosis, mutational status, DNA methylation, RNA methylation, TMB, TMB, MSI, and drug sensitivity across various cancer types." (PMID 40526173, 2025). "Accumulated evidence has demonstrated that DDX17 is dysregulated in diverse types of cancers." (PMID 39897048, 2025). "However, current research on DDX17 primarily focuses on a limited number of cancer types, and its roles in other tumors remain to be further explored." (PMID 40526173, 2025). "Aberrant expression of DDX17 has been observed in various tumor types, and it plays a pivotal role in tumorigenesis, as well as cancer cell proliferation, invasion, and metastasis through intricate mechanisms such as RNA binding, transcriptional regulation, and microprocessor complex formation." (PMID 40526173, 2025). "Collectively, these results highlight DDX17 as a promising prognostic biomarker in cancer." (PMID 40526173, 2025). "The involvement of DDX17 in these processes suggests that it may play a central role in regulating cancer-related RNA metabolism, making it a potential therapeutic target for cancers with dysregulated RNA processing." (PMID 40526173, 2025). "Furthermore, the levels of DDX17 in serum and cancer tissues are also correlated with tumor metastasis." (PMID 41322492, 2025). "Additionally, we investigated the relationship between DDX17 mRNA levels and the sensitivity of anti-cancer drugs." (PMID 40526173, 2025).